ENSG00000283041 (eukaryotic translation elongation factor 1 gamma ()
Synonyms: LOC729998
Gene: Processed pseudogene on chromosome 7 (133,034,607 to 133,035,920, reverse strand). Ensembl gene ENSG00000283041.
Diseases named in the same sentence as ENSG00000283041 in open-access papers:
ENSG00000283041 is named in the same sentence as 2 diseases in open-access papers, as found by Europe PMC text mining. Sharing a sentence is not in itself a finding about the gene and the disease. The quoted sentences say what the papers report.
tumor (1 paper, 2017). "In the present study we identified four candidate tumor-associated antigens, including chaperonin containing TCP1 subunit 5 (CCT5), heat shock 70 kDa protein 8 isoform 1 (HSP70), eukaryotic translation elongation factor 1 gamma (eEF1), and phosphoglycerate mutase 1 (PGM1)." (PMID 28969060, 2017).
ENSG00000283041 also shares sentences with these, for which no sentence is quoted: cancer (2 papers).